MRPL55 (mitochondrial ribosomal protein L55)
Synonyms: MRP-L55; bL31m; AAVG5835; L55nt; PRO19675
Tractability: Small molecule: a structure with a bound ligand is known. PROTAC: its protein half-life has been measured.
Gene: Protein-coding gene on chromosome 1 (228,105,949 to 228,109,358, reverse strand). Ensembl gene ENSG00000162910.
Subcellular location: Mitochondrion
Pathways (Reactome):
Metabolism of proteins: Mitochondrial ribosome-associated quality control; Mitochondrial translation elongation; Mitochondrial translation initiation; Mitochondrial translation termination
Gene Ontology:
Molecular function: structural constituent of ribosome
Biological process: mitochondrial translation; translation
Cellular component: mitochondrial large ribosomal subunit; mitochondrion; mitochondrial inner membrane
Genetic constraint (gnomAD): Loss-of-function variants: 10 observed, 15.19 expected, observed/expected ratio (o/e) 0.66, 90% interval 0.41 to 1.12. The upper end of that interval is the gene's LOEUF score, 1.12, which puts it in group 4 of 6, group 1 being the genes least tolerant of losing a copy. Missense variants: 148 observed, 187.96 expected, observed/expected ratio (o/e) 0.79, 90% interval 0.69 to 0.9. Synonymous variants: 57 observed, 76.07 expected, observed/expected ratio (o/e) 0.75, 90% interval 0.61 to 0.93.
Homologues: Orthologues: chimpanzee MRPL55 (98% identical), guinea pig MRPL55 (76% identical), dog MRPL55 (71% identical), mouse Mrpl55 (71% identical), rabbit MRPL55 (69% identical), pig MRPL55 (68% identical), rat Mrpl55 (52% identical).
Diseases named in the same sentence as MRPL55 in open-access papers:
MRPL55 is named in the same sentence as 5 diseases in open-access papers, as found by Europe PMC text mining. Sharing a sentence is not in itself a finding about the gene and the disease. The quoted sentences say what the papers report.
ovarian carcinoma (3 papers, 2021 to 2024). A malignant neoplasm originating from the surface ovarian epithelium. "MRPL55 can also be used as an observational indicator for the prognosis of ovarian cancer patients." (PMID 39254691, 2024).
hepatocellular carcinoma (1 paper, 2024). A malignant tumor that arises from hepatocytes. "An increase in the MRPL55 level in hepatocellular carcinoma can serve as a potential diagnostic marker." (PMID 39254691, 2024).
metabolic disease (1 paper, 2021). A congenital disorder (due to inherited enzyme abnormality) or acquired (due to failure of a metabolically important organ) disorder resulting from an abnormal metabolic process. "The disorders known to be associated with the affected genes range from embryonic lethality (e.g., MRPL55 and LIG3) and metabolic diseases (e.g. acyl-CoA synthetase long chain family member 5 (ACSL5)) to neurodevelopmental disorders (e.g., methionyl-tRNA synthetase 2 (MARS2))." (PMID 34915862, 2021).
tumor (1 paper, 2019). "MRPL55 is one of the mitoribosome-specific proteins, which are reported to play an important role in the regulation of cell death and act upon tumor suppressors." (PMID 31443718, 2019).
MRPL55 also shares sentences with these, for which no sentence is quoted: neurodevelopmental disorder (1 paper).